RNU6-1334P (RNA, U6 small nuclear 1334, pseudogene)
Gene: Small nuclear RNA gene on chromosome Y (2,784,749 to 2,784,853, forward strand). Ensembl gene ENSG00000251841.
Homologues: Orthologues: chimpanzee U6 (96% identical). Paralogues in human: RNU6-434P (78% identical), RNU6-35P (77% identical), RNU6-29P (76% identical), RNU6-854P (76% identical), RNU6-1013P (75% identical), RNU6-1075P (75% identical), RNU6-1181P (75% identical), RNU6-25P (75% identical), RNU6-339P (75% identical), RNU6-41P (75% identical), RNU6-692P (75% identical), RNU6-836P (75% identical), and 1286 more.